Y_RNA (Y RNA )
Gene: Miscellaneous RNA gene on chromosome 14 (72,853,224 to 72,853,331, reverse strand). Ensembl gene ENSG00000206751.
Homologues: Orthologues: chimpanzee Y_RNA (99% identical), macaque Y_RNA (92% identical). Paralogues in human: RNY1P5 (86% identical), Y_RNA (86% identical), Y_RNA (85% identical), RNY1 (84% identical), Y_RNA (84% identical), Y_RNA (83% identical), Y_RNA (82% identical), Y_RNA (81% identical), RNY1P11 (81% identical), RNY1P6 (80% identical), Y_RNA (80% identical), RNY1P1 (79% identical), and 93 more.